NLRP3 (NLR family pyrin domain containing 3)
Diseases named in the same sentence as NLRP3 in open-access papers (continued):
Sharing a sentence is not in itself a finding about the gene and the disease.
Sepsis (continued). "Active NLRP3 promotes the secretion of the cytokines IL-1β and the cysteine proteases (caspase-1), which are considered protective during initial process of sepsis." (PMID 30779706, 2019). "While little information about this exists, our data show that sepsis-triggered canonical inflammasome depends on the NLRP3/caspase-1 pathway for the maturation and secretion of IL-1β and on GSDMD for the induction of pyroptosis." (PMID 30276509, 2019). "Here, we study a cohort of individuals with intra-abdominal origin sepsis and show that patient monocytes have impaired NLRP3 activation by the P2X7 receptor." (PMID 31221993, 2019). "Four NLRP3 compromised patients survived sepsis, and from them we were able to obtain a sample from three patients once recovered." (PMID 31221993, 2019). "Our findings suggest that the role of VDR signaling in sepsis is largely dependent on NLRP3-induced inflammation." (PMID 31866999, 2019). "We show for the first time that NLRP3 is activated in platelets stimulated by LPS or sepsis in CLP rats." (PMID 31054188, 2019). "•STING-IRF3 triggers cardiac injury by activating NLRP3 inflammasome in sepsis-induced cardiomyopathy." (PMID 31121492, 2019). "We postulate platelet NLRP3 activation to be relevant not only to the understanding of the mechanisms of sepsis‐induced organ dysfunction, but also a novel therapeutic target." (PMID 31054188, 2019). "Here, using a cohort of patients with intra-abdominal origin sepsis, the authors show an important role for the NLRP3 inflammasome in establishing a host response, and NLRP3 dysfunction is a common feature of sepsis mortality." (PMID 31221993, 2019). "To address the cross-talk between VDR and NLRP3 in vivo, we next induced sepsis in Vdr−/−, Nlrp3−/−, and Vdr−/−/Nlrp3−/− mice by intraperitoneal injection of LPS (8 mg/kg)." (PMID 31866999, 2019). "In an in vivo experiment, PKA activation attenuated both LPS-induced sepsis and alum-induced peritonitis via suppression of NLRP3 inflammasome activation." (PMID 29868015, 2018). "In the present study, we demonstrate that BMSCs exert beneficial effects on experimental sepsis via inhibiting NLRP3 inflammasome activation in macrophages." (PMID 29636842, 2018). "The inflammasome inter alia consists of NLR family pyrin domain containing 3 (NLRP3) which is up-regulated in sepsis." (PMID 29449936, 2018). "Using a model of sepsis, it was recently delineated that NLRP3 inflammasome activation itself is regulated by fatty acid synthase (Fasn)-dependent lipid synthesis." (PMID 30315247, 2018). "Previous researches showed that the NLRP3 inflammasome was upregulated and activated in the liver during sepsis." (PMID 29636842, 2018). "The activation of NLRP3 inflammasome has been suggested to play important roles in sepsis, which is currently defined as life threatening organ dysfunction caused by a dysregulated host response to infection." (PMID 29375379, 2017). "Whereas sepsis led to a decreased Myh2 and Myh7 expression in muscle of WT, this effect was blunted in Nlrp3 KO." (PMID 28097512, 2017). "This atrophic response was attenuated in Nlrp3 KO compared to WT following sepsis as indicated by a less pronounced reduction in mean MCSA in septic Nlrp3 KO." (PMID 28097512, 2017). "On the other hand, blockade of pyroptosis by caspase-1/-11 or gasdermin D gene deletion renders mice resistant to endotoxin-induced sepsis, suggesting NLRP3 and other inflammasome activation play a critical role in sepsis." (PMID 29375379, 2017). "We performed qRT-PCR to investigate if sepsis increases Il1b or Nlrp3 expression in gastrocnemius/plantaris or tibialis anterior muscle of mice and found that sepsis induced Il1b and Nlrp3 expression in both muscles." (PMID 28097512, 2017). "We found that depletion of Nlrp3 in mice not only increases their survival in sepsis but also inhibits sepsis and inflammation-mediated muscle atrophy." (PMID 28097512, 2017).
Sepsis (continued). "Of the novel genes, UCP2 is highly down-regulated in treatment failures compared to cures at pre-treatment baseline and has been shown to be involved in fatty acid metabolism that promotes NLRP3 inflammasome activation during sepsis." (PMID 29050771, 2017). "This also suggests that activation of NLRP3 is critical for proinflammatory response and even sepsis in vivo." (PMID 28321151, 2017). "Aging and sepsis triggered NLRP3 inflammasome activation, which has been shown to be involved in the innate immune response during inflammation." (PMID 28596733, 2017). "As NLRP3-dependent release of IL-1β has a critical role in sepsis, the in vivo activity of scutellarin was assayed in a mouse model of bacterial sepsis, which was established by intraperitoneally injection of a lethal dose of viable Escherichia coli." (PMID 29375379, 2017). "Polymicrobial sepsis was induced by cecum ligation and puncture surgery in Nlrp3 knockout and wild type mice." (PMID 28097512, 2017). "Together, these data suggested that CORM-2 treatment inhibit the NLRP3 inflammasome activation in sepsis-induced AKI." (PMID 26334271, 2015). "In our study, CO inhibited the NLRP3 inflammasome activation and decreased the sepsis-induced AKI in rats." (PMID 26334271, 2015). "Several studies have shown that dysregulated NLRP3 inflammasome activation participates in the pathogenesis of sepsis and AKI." (PMID 26334271, 2015). "Further, we show that blockade of the NLRP3 inflammasome/caspase-1/IL-1β pathway can afford protection against lethality in a model of polymicrobial sepsis." (PMID 25216263, 2014). "Although our findings strongly support a role for the NLRP3 inflammasome/caspase-1/ IL-1β pathway of CFs in the myocardial dysfunction, as well as, lethality in sepsis, extrapolation to the human condition is rather tenuous." (PMID 25216263, 2014). "Our results indicate that the activation of the NLRP3 inflammasome in cardiac fibroblasts is pivotal in the induction of myocardial dysfunction in sepsis." (PMID 25216263, 2014). "In the present study, we provide evidence indicating that the NLRP3 inflammasome in CFs is activated in sepsis and increases IL-1β production." (PMID 25216263, 2014). "Although these isolated observations support a potential role for the NLRP3 inflammasome/caspase-1/IL-1β pathway, the present study is the first to provide a systematic assessment of this pathway in endotoxemia/sepsis both in vivo and in vitro." (PMID 25216263, 2014). "Taken together, our data indicate that 14-3-3ε functions as a positive regulator of the NLRP3 inflammasome and could be a target for sepsis treatment." (PMID 41480749, 2026). "Furthermore, both in vivo and in vitro experiments demonstrated that XQHF modulates sepsis-induced acute lung injury, at least in part, through the inhibition of the NLRP3/Caspase-1-dependent pyroptosis signaling pathway." (PMID 41710028, 2026). "Mass spectrometry revealed that 14-3-3ε binds to NLRP3 in macrophages during sepsis." (PMID 41480749, 2026). "Hence, enhancing the restoration of mitochondrial functionality and the elimination of ROS to suppress the activation of the NLRP3 inflammasome is of significant importance in the management of sepsis." (PMID 40809343, 2025). "Notably, NLRP3 activation also contributes to the immunosuppressive phase of sepsis by promoting immune cell exhaustion and metabolic reprogramming, which perpetuate long-term immune dysfunction." (PMID 40558557, 2025). "In sepsis models, the activation of miR‐138‐5p promoter methylation leads to the downregulation of miR‐138‐5p expression, thereby promoting the activation of the NLRP3 inflammasome and inducing pyroptosis." (PMID 40821693, 2025). "Experiments conducted both in a laboratory setting and in living organisms demonstrated a notable increase in the levels of NLRP3 and IL-1β expression in Kupffer cells in a sepsis model induced by LPS, highlighting their strong response to the pyroptosis pathway." (PMID 40458798, 2025).
Sepsis (continued). "Similarly, the IL‐17 signalling pathway promotes cellular pyroptosis in pneumonia‐induced Sepsis through activation of NLRP3 inflammatory vesicles." (PMID 39993996, 2025). "GLP-1 RAs may reduce sepsis risk by suppressing inflammation, including cytokine production and monocyte adhesion, as shown in animal studies via STAT3 and NLRP3 pathways." (PMID 40863575, 2025). "YTHDF1 can positively regulated the expression of WW domain containing E3 ubiquitin protein ligase 1 (WWP1) expression through RNA modifications, which increases the ubiquitination of NLRP3 and subsequetly decreases NLRP3 expression levels, thereby alleviating sepsis." (PMID 41373022, 2025). "During the pathogenesis of sepsis, macrophages are exposed to various environmental stresses, including oxidative stress, which may induce the formation of NLRP3 inflammasomes." (PMID 40918153, 2025). "It has been found that the activation of NLRP3 plays a role in many chronic inflammatory diseases, and molecular H2 can effectively inhibit the activation of NLRP3 to ameliorate endometrial cancer, kidney inflammation, septicemia, neuropathic pain, and so on." (PMID 40297245, 2025). "The NLRP3 inflammasome is instrumental in driving sepsis-induced pyroptosis in endothelial cells." (PMID 41280722, 2025). "Targeted NLRP3 inhibition during the early to mid‐phases of sepsis progression may help restore immune equilibrium by reducing pro‐inflammatory cytokine release while avoiding suppression of anti‐inflammatory mediators." (PMID 40599085, 2025). "Similarly, MCC950 has been shown to suppress NLRP3 inflammasome activation, leading to reduced platelet activation and cytokine production in experimental models of sepsis." (PMID 40649892, 2025). "The authors suggested that excessive activation of NLRP3 may lead to the release of endogranulinic acid (Eicosanoid) through the pyroptosis pathway, which could intensify sepsis." (PMID 40458798, 2025). "In sepsis-induced ALI, Z-DNA-binding protein 1 (ZBP1) deficiency in macrophages mitigates mitochondrial damage, consequently reducing macrophage pyroptosis mediated by NLRP3 inflammasome activation." (PMID 40028334, 2025). "Our research results demonstrate that ECG alleviates sepsis-induced ALI by inhibiting the NLRP3/Caspase-1/GSDMD signaling pathway-mediated pyroptosis, the Bcl-2/Bax/Caspase-3 signaling pathway-mediated apoptosis, and regulating the ZBP1/MLKL/RIPK1 signaling pathway-mediated necroptosis." (PMID 41496909, 2025). "Furthermore, the FDA-approved antidiarrheal drug nifuroxazide improves cardiac structure by suppressing the TLR4/NLRP3 pathway in LPS-induced cardiac inflammation 172, although NLRP3's role in sepsis-induced myocardial injury remains in early investigation." (PMID 40520010, 2025). "This section reviews the design, characterization, and therapeutic potential of different types of nanocarriers, including inorganic, protein‐based, dendrimer‐based, lipid‐based, and polymer‐based carriers, in the context of NLRP3 inflammasome inhibition against sepsis." (PMID 40599085, 2025). "Incorporation of recent insights regarding proteasome-mediated degradation of viral and bacterial proteins and MAPK’s role in sepsis and inflammation offers further context on the complexity of NLRP3 regulation and highlights potential combinational strategies for inflammatory disease management." (PMID 41155878, 2025). "In addition, phospholipase D2 (PLD2) deletion ameliorates sepsis-induced cardiomyopathy by suppressing cardiomyocyte pyroptosis via the NLRP3/caspase-1/GSDMD pathway." (PMID 40708650, 2025). "Additionally, the lack of SIRT3 enhances lung endothelial pyroptosis by disrupting mitophagy, leading to the activation of the NLRP3 inflammasome and worsening sepsis‐induced ALI." (PMID 40821693, 2025). "Consequently, the use of NLRP3-inhibitors has the potential to ameliorate the clinical course in such patients and prevent fatal outcomes from uncontrolled sepsis." (PMID 41019046, 2025).
Sepsis (continued). "NLRP3 inflammasome contributes to sepsis development, and its inhibition can lessen its severity." (PMID 41041277, 2025). "USP7 upregulated SOX9 expression through deubiquitination, and SOX9 suppressed miR-96-5p expression by binding to the miR-96-5p promoter region, thereby promoting NLRP3 expression and then exacerbating sepsis-induced myocardial injury and cardiomyocyte pyroptosis." (PMID 40041174, 2025). "Here, we found that hnRNPA2B1 positively regulated NLRP3 inflammasome activation in macrophages, suggesting that targeting its activity could offer potential therapeutic strategies for sepsis." (PMID 39887250, 2025). "NLRP3 activation in sepsis represents a pivotal event in tissue injury." (PMID 40959087, 2025). "These agents also limit NLRP3 priming and oxidative stress, restore antioxidant defenses, and preserve mitochondrial homeostasis across models of liver injury, neuroinflammation, metabolic dysfunction, and sepsis." (PMID 41373468, 2025). "We aim to determine whether Fas suppresses the STAT-3 and NLRP-3 pathways, which are crucial to sepsis-related inflammation and immune responses." (PMID 40699739, 2025). "In light of the previously published results, the current study evaluated if CLM might prevent liver damage brought on by sepsis, for the first time, by preventing NLRP-3/Caspase-1 pathway-mediated pyroptotic cell death in rats." (PMID 40770673, 2025). "Meanwhile, it can inhibit NLRP3 inflammasome activation and attenuate the level of inflammatory factors, reduce the production of inflammatory factor storms, alleviate the condition of sepsis and effectively improve organ dysfunction." (PMID 40809343, 2025). "Moreover, S100A12 has been found to induce inflammation and apoptosis in septicemia-induced ARDS by activating the NLRP3 inflammasome signaling pathway." (PMID 40655156, 2025). "To further elucidate the relationship between p62 and pyroptosis in SAE, p62, and NLRP3 co‐staining was conducted, and we found that the numbers of p62‐NLRP3‐positive cells were higher after sepsis than the Sham group, whereas it was reduced after Mdivi‐1 administration in vivo." (PMID 39791542, 2025). "The cumulative evidence implies that administration of exogenous NAD+ to restore mitochondrial function and suppress the NLRP3 inflammasome pathways could represent an optimal therapeutic approach for sepsis treatment." (PMID 40809343, 2025). "Furthermore, the study discovered that Sestrin2 (SESN2) effectively suppressed excessive activation of the NLRP3 inflammasome and the resulting caspase-1-dependent pyroptosis, leading to an enhanced prognosis in sepsis." (PMID 38816685, 2024). "As a type of gas with small molecules possessing the proper distribution characteristics to penetrate membranes and diffuse into organelles, methane has been proposed to be a new therapeutic gas for sepsis-induced intestinal injury involving the inhibition of NLRP3-mediated pyroptosis." (PMID 37898993, 2024). "Moreover, we also found that rh PLTP treatment inhibited the activation of the NLRP3 inflammasome/GSDMD signaling pathway in the heart tissue of mice with sepsis." (PMID 38584827, 2024). "In sepsis, the occurrence of macrophage pyroptosis was observed, and the survival rate of septic mice was enhanced by inhibiting the inflammatory response of macrophages through NLRP3 knockout, leading to an improvement." (PMID 38816685, 2024). "In summary, NCTP could alleviate sepsis-induced acute lung injury by regulation of the NLRP3 and TLR-4/NF-κB pathways and the gut microbiota." (PMID 38673868, 2024). "Thus, we further confirmed that downregulation of HSPA8 in sepsis activated the NLRP3 inflammasome by reducing the ubiquitination level of NLRP3." (PMID 38698431, 2024). "This study revealed that NLRP3 activation is beneficial for ALD hosts in maintaining the intestinal epithelial barrier, potentially offering insights into the treatment and prognosis of sepsis in susceptible populations with liver disease." (PMID 39605303, 2024).
Sepsis (continued). "In summary, we hypothesized that circMAPK1 facilitated KDM2B mRNA decay via recruiting UPF1, and the inhibition of KDM2B-mediated WNK1 demethylation further suppressed WNK1 expression, thus triggering NLRP3-mediated pyroptosis in sepsis-induced ALI." (PMID 39300342, 2024). "TSP-1 deficiency protects mice against sepsis-induced AKI by decreasing the expression of inflammatory and apoptosis-promoting cytokines, such as the NLRP3 inflammasome, caspase-1, IL-1β, and IL-18, which increase cell viability and partially reverse cell pyroptosis." (PMID 38516004, 2024). "In this study, we found that ADAR1 regulated sepsis-induced pyroptosis in pulmonary macrophages via the miR-21/A20/NLRP3 axis, which could help guide future therapeutic interventions that target this pyroptotic signalling pathway in sepsis-induced lung injury." (PMID 38169584, 2024). "Overall, our results reveal a mechanism by which the PADIs/NLRP3/Ym1 pathway influences macrophage behavior in sepsis, suggesting that targeting this pathway could alleviate the inflammatory response in PA-induced ALI and improve survival." (PMID 39405117, 2024). "Therefore, the NLRP3 inflammasome plays a significant role in the progression of acute kidney injury, albeit its precise role and mechanisms in sepsis-induced acute kidney injury remain poorly understood." (PMID 39839617, 2024). "Similarly, we and others have demonstrated the detrimental role of the NLRP3 inflammasome during sepsis." (PMID 38720893, 2024). "Contrastingly, C12 AMs emerged as a marked population post-sepsis (0.1% in WT Sham versus 43.7% in WT PA), characterized by a distinct proinflammatory signature with elevated expression of the inflammasome Nlrp3 gene, alongside increased levels of proinflammatory cytokine and chemokine genes." (PMID 39405117, 2024). "In sepsis, the increase of NLRP3 protein level is related to its ubiquitination modification." (PMID 38698431, 2024). "However, in mice that were administered BRD3308 and subsequently challenged with sepsis, both macrophage infiltration and NLRP3 expression were markedly suppressed." (PMID 39224841, 2024). "In conclusion, the present study demonstrates that the suppression of HSPA8 promotes the degradation of SKP2, which in turn attenuates the ubiquitination and degradation of NLRP3 protein, leading to the activation of NLRP3 inflammasome and subsequent AECs pyroptosis in during sepsis." (PMID 38698431, 2024). "mitophagy induced the demethylation of the miR-138-5p promoter, which may subsequently inhibit NLRP3 inflammasome, AM pyroptosis and inflammation in sepsis-induced lung injury." (PMID 39234245, 2024). "In a LPS‐induced sepsis‐associated encephalopathy model, the NU9056 treatment group exhibited an increase in Verrucomicrobia and Akkermansia, along with a significant reduction in NLRP3 inflammasome activity, alleviating the inflammatory response." (PMID 39568773, 2024). "Other studies have demonstrated that exogenous NRG1 administration attenuates oxidative stress and inflammation by inhibiting the production of reactive oxygen species IL-1β and NLRP3 inflammasome, and supports cardiac repair, sepsis, traumatic spinal cord injury." (PMID 39312480, 2024). "The miR-21/A20/NLRP3 signalling cascade, which may be thought of as an intervention target for the treatment of sepsis-related lung disorders, was responsible for these results." (PMID 38169584, 2024). "In conclusion, our findings illustrated that circMAPK1 promoted KDM2B mRNA decay via recruiting UPF1, thereby inhibiting KDM2B-mediated WNK1 demethylation to suppress WNK1 expression, and ultimately triggering NLRP3-mediated pyroptosis to exacerbate sepsis-induced lung injury." (PMID 39300342, 2024). "Therefore, we concluded that ACSS2 deletion mitigated the activation of the NLRP3 inflammasome and decreased pyroptosis in RTECs of the mouse LPS-induced sepsis model." (PMID 38515158, 2024).